INS (insulin)
Diseases named in the same sentence as INS in open-access papers (continued):
Sharing a sentence is not in itself a finding about the gene and the disease.
Insulin resistance (continued). "The secondary outcome include fasting plasma glucose, blood lipids, C-peptides, insulin, inflammatory factors, insulin resistance index (HOMA-IR) and the subcutaneous and visceral fat content in the upper abdomen measured by MRI." (PMID 37076915, 2023). "Second, obesity increases insulin resistance and raises circulating insulin levels, which can lead to type 2 diabetes." (PMID 37298013, 2023). "Several studies have revealed the impact of methylglyoxal on insulin signaling pathways and insulin resistance and recently this metabolite has been introduced as an emerging marker for T2DM diagnosis." (PMID 37319295, 2023). "HFD feeding for 20 weeks induced MetS by increasing body weight, insulin levels, homeostasis model assessment of insulin resistance (HOMA-IR), and lipid levels, including cholesterol and triglycerides as compared to low-fat diet (LFD) feeding." (PMID 37176029, 2023). "During the diabetic condition, significantly reduced levels of GLP-1 lead to impaired insulin activity and progressive insulin resistance." (PMID 37189744, 2023). "Insulin levels were increased and insulin resistance was seen in children with poorly controlled asthma when compared to well-controlled asthma." (PMID 37362491, 2023). "Based on these findings, T2D patients with higher blood glucose levels are considered to have a greater demand for exogenous insulin because hyperglycemia per se reflects lower insulin secretion in addition to insulin resistance." (PMID 36658284, 2023). "In this review, we discuss the role of autophagy in the target tissues of insulin with a focus on its contribution to the pathophysiology of insulin resistance." (PMID 37876013, 2023). "Homeostatic model assessment for insulin resistance (HOMA-IR) or other indices derived from insulin measurement is widely used in daily practice." (PMID 35765946, 2023). "That is, peripheral insulin resistance can disrupt brain insulin activity and vice versa, thus leading to a vicious cycle." (PMID 37867511, 2023). "In line with our results, an RCT study reported that receiving 1800 mg of NAC for 12 weeks significantly reduced all glycemic factors, including fasting glucose and insulin, as well as improved insulin resistance." (PMID 37794966, 2023). "This study aimed to observe the expression of insulin-signaling molecules in different organs of mice with insulin resistance (IR)." (PMID 37830511, 2023). "When insulin resistance increases owing to a decrease in insulin sensitivity, glucose cannot normally enter the cells of insulin-sensitive tissues, and gluconeogenesis increases in the liver, inducing an increase in fasting blood glucose." (PMID 37432173, 2023). "Insulin resistance is a condition in which body tissues become resistant to insulin, leading to disturbances in lipid and glucose metabolism." (PMID 38094123, 2023). "Long term studies echo these benefits, revealing that sustained pulse intake significantly decreases levels of FBG, HbA1c, fasting insulin, markers of insulin resistance such as HOMA-IR, and indicators such as high C-peptide levels." (PMID 37836506, 2023). "We calculated genetic risk scores (GRS) of first phase insulin release (FPIR), fasting insulin (FI), combined insulin resistance and dyslipidaemia (IR + DLD) and insulin sensitivity (IS) in a study population of 665 genotyped newborns." (PMID 37949941, 2023). "In SLE, the systemic inflammation and release of proinflammatory cytokines negatively affect insulin signaling and result in insulin resistance." (PMID 38505536, 2023). "Insulin resistance induced by obesity is characterized by a dysfunction of insulin to activate the IRS/phosphoinositide 3-kinase/AKT pathway, leading to suppression of the insulin-induced glucose uptake in the insulin-sensitive organs, such as the liver." (PMID 37114144, 2023).
Insulin resistance (continued). "Omentin has been found to improve insulin sensitivity in animal studies, and lower levels of omentin have been observed in individuals with insulin resistance." (PMID 37600709, 2023). "The homeostatic model assessment for insulin resistance (HOMA-IR) was used to quantify fasting insulin resistance [(PG in mmol/L × insulin in μIU/mL)/22.5]." (PMID 37252699, 2023). "T2D is a multifactorial metabolic disorder marked by dysregulated glucose homeostasis, insulin resistance, and impaired insulin secretion." (PMID 37510368, 2023). "The number of exosomes in peripheral blood or adipocyte-derived exosomes positively correlated with the insulin resistance index (HOMA-IR) to assess the homeostasis model, also associated with insulin sensitivity." (PMID 36818396, 2023). "The disposition index, acute insulin response to glucose, insulin resistance, plasma insulin, glucose, and HBA1C progressively worsened in the following order: control, OSA, T2DM, and T2DM + OSA (p for trend <0.05)." (PMID 36982383, 2023). "On the other hand, TZDs are known to reduce insulin resistance by increasing insulin-dependent glucose disposal and reducing hepatic glucose output." (PMID 37362539, 2023). "The enhancement of glycemic regulation attributed to vitamin D arises from its ability to mitigate peripheral insulin resistance, modify immune responses and systemic inflammation, and stimulate insulin secretion." (PMID 38022364, 2023). "This study demonstrated a significant decrease in TNF‐α and IL‐1β levels, a decrease in insulin secretion, a reduction in insulin resistance symptoms, and an increase in HOMA‐β levels in each intervention group." (PMID 37181308, 2023). "The group with BED exhibited the highest plasma insulin and insulin resistance among the groups, confirming previous findings." (PMID 37726785, 2023). "Glucose, insulin, homeostatic model assessment for insulin resistance, glutathione peroxidase, superoxide dismutase, oxidized LDL, and malondialdehyde did not significantly change after 4 weeks in any group." (PMID 37049398, 2023). "Prior to the beta cell failure that often occurs over time, pancreatic beta cells respond to insulin resistance with increased insulin secretion, resulting in hyperinsulinemia." (PMID 37990681, 2023). "The emergence of insulin resistance is evidenced by the inability of insulin to lower glucose from baseline levels." (PMID 38389818, 2023). "In patients with type 2 diabetes, both insulin action (insulin resistance) and insulin secretion are impaired, with one of these abnormalities playing a predominant role, depending on the stage of the disease." (PMID 36773074, 2023). "Impaired insulin clearance leads to progressive insulin resistance, potentially due to the development of chronic hyperinsulinemia." (PMID 37960324, 2023). "T2DM is a state of hyperglycemia that can be the result of insulin resistance or abnormal insulin secretion." (PMID 37834407, 2023). "While, reduced physical activity and vitamin D deficiency are related to increased adiposity, blood glucose level, insulin concentration, and insulin resistance." (PMID 37353689, 2023). "In the state of insulin resistance, the inhibition of downstream insulin signal transduction activates GSK3β; thus, glycogen production is attenuated." (PMID 37569816, 2023). "In the present study, the interdisciplinary therapy was effective in improving glucose, insulin, and both indicators of insulin resistance and insulin sensitivity, HOMA-IR and QUICKI, respectively." (PMID 38063544, 2023). "This disruption impedes the process of tyrosine phosphorylation, resulting in impaired insulin signaling and subsequent insulin resistance." (PMID 37608322, 2023). "Insulin resistance is characterised by attenuated insulin induced-GLUT4 trafficking and GLUT4 down-regulation in adipose tissue." (PMID 36283703, 2023).
Insulin resistance (continued). "This ability of chlorella to modulate insulin signaling pathways seems to also be related to its activity on muscle sirtuin 1 (SIRT1), as increased expression of SIRT1 improves insulin sensitivity and attenuates insulin resistance." (PMID 37432326, 2023). "This type of DM is a chronic disease manifested by the elevated level of glucose in the blood resulting primarily from insulin resistance which over time is joined by a defect in insulin secretion." (PMID 36975496, 2023). "Previous research on mice lacking Epac2A (Epac2A KO) has demonstrated a propensity for obesity, a diminished first phase of insulin secretion, and impaired glucose-stimulated insulin secretion under diet-induced insulin resistance." (PMID 37701894, 2023). "During insulin resistance conditions such obesity, hypertension, and type 2 diabetes, insulin-mediated glucose transport is reduced in the skeletalmuscle." (PMID 37822828, 2023). "Type 2 Diabetes (T2D) is characterized by high blood glucose levels and develops due to inadequate pancreatic β-cell function (i.e., insulin secretion) and peripheral insulin resistance." (PMID 36980190, 2023). "In insulin resistance, higher insulin levels leads to reduced synthesis and secretion of sex hormone binding globulin (SHBG) levels by the liver." (PMID 37836508, 2023). "In multiple obese animal models, resistin was shown to induce insulin resistance, where hyper-resistinemia remarkably impairs insulin sensitivity." (PMID 38149100, 2023). "The effect on biochemical measures, such as fasting blood sugar (FBS), post-meal blood sugar (PMBS), insulin, glucose-to-insulin ratio, lipid profile, and the Homeostatic Model Assessment for Insulin Resistance (HOMA-IR), was analyzed in 10 papers." (PMID 37575860, 2023). "Inositol and phosphatidylinositol reduce insulin resistance, improve insulin sensitivity, and have unique roles in energy metabolism and metabolic disorders." (PMID 38098862, 2023). "In parallel with systemic insulin resistance, all treatments blunted insulin-induced GLUT4 recruitment to the sarcolemma in the gastrocnemius." (PMID 37229459, 2023). "The interaction effect of dietary choline and moderate or high physical activity improved insulin resistance (decreasing insulin and HOMAIR and increasing QUICKI) (P < 0.05)." (PMID 37491240, 2023). "Reduced mitochondrial function can lead to decreased ATP production, which can impair insulin signaling and glucose uptake, contributing to the development of insulin resistance." (PMID 37445955, 2023). "For miR-21, a previous study showed that this miRNA reversed insulin resistance in 3T3-L1 cells and significantly increased insulin-induced glucose uptake by translocating GLUT4 to the cell membrane." (PMID 38132872, 2023). "The metabolic benefits in patients with T2D were quite convincing, with marked improvements in fasting insulin, glucose, and HbA1c levels and a reduction in insulin resistance." (PMID 37171643, 2023). "Chromium, for instance, can reduce insulin resistance and enhance insulin sensitivity via cell receptors." (PMID 38024820, 2023). "Studies have shown that changes in myocardial substrate utilization, insulin resistance, and impaired insulin signaling, can disrupt mitochondrial morphology and function." (PMID 37005683, 2023). "Excessive adipose tissue, especially in visceral depots, induces a state of chronic low-grade inflammation and dysregulated secretion of adipokines, impairing insulin signaling pathways and exacerbating insulin resistance." (PMID 37978556, 2023). "Abnormalities in insulin-sensitive tissues, such as the liver, in terms of triglyceride storage and lipolysis were early indicators of insulin resistance." (PMID 36992148, 2023). "The results of the OGTT and ITT revealed that HFD-fed mice showed impaired glucose metabolism and insulin resistance, whereas A. muciniphila administration improved insulin sensitivity and exerted a better tolerance to glucose load in HFD mice." (PMID 37893609, 2023).
Insulin resistance (continued). "DM is a chronic disease created via insufficient insulin production/secretion from the pancreas or via insulin resistance." (PMID 36674648, 2023). "Primary outcomes included pre/post-fasting glucose, insulin, inflammatory markers, and homeostasis model assessment of insulin resistance (HOMA-IR)." (PMID 38068805, 2023). "Numerous investigations have demonstrated a tight connection between insulin and the development of type 2 diabetes, meanwhile, insulin resistance has adverse effects on the progression of atherosclerosis and CVD." (PMID 37534205, 2023). "Metformin as well as thiazolidinediones, both of which are insulin sensitizers, improve insulin resistance in PCOS." (PMID 36408981, 2023). "Prior studies in rodents have assessed insulin resistance by giving a challenge injection of insulin and measuring the degree to which peripheral glucose levels are reduced." (PMID 38389818, 2023). "Sirt7 KO mice are resistant to HFD-induced obesity, insulin resistance, and glucose intolerance, indicating that SIRT7 deficiency improves insulin sensitivity and glucose homeostasis in vivo." (PMID 38201252, 2023). "Levels of the fasting blood glucose, fasting insulin, and homeostasis model assessment of insulin resistance (HOMA-IR) index were significantly decreased in HFD-fed Bach1LKO mice with respect to the control mice." (PMID 38129407, 2023). "Persistent insulin resistance exhausts the ability of pancreatic beta cells to provide the required amounts of insulin, further disrupting glucose homeostasis." (PMID 37772082, 2023). "In a study of Cannabidiol, researchers observed that cannabidiol inactivated GSK-3 in the rats treated with a high-fat diet, leading to increased insulin sensitivity and thus reducing the occurrence of cerebral insulin resistance." (PMID 37867511, 2023). "This is particularly significant for insulin resistance etiologies originating from liver, as insulin-mediated pathways, including the cellular uptake of glucose, fatty acid synthesis, and fatty acid oxidation, are disrupted with obesity and liver pathologies." (PMID 38140297, 2023). "Dexamethasone induces insulin resistance by inhibiting the action of insulin; that is, by stimulating the production of glucose in the liver and reducing the use of glucose in the peripheral tissues." (PMID 37396152, 2023). "Body mass index, blood pressure, fasting glycemia, insulin resistance, and serum insulin levels are all inverse relationships with serum adiponectin levels." (PMID 37218883, 2023). "This is because smoke changes high-density lipoprotein cholesterol, plasma glucose, immunoreactive insulin, and insulin resistance." (PMID 36673895, 2023). "(D) Small molecules that reverse palmitate induced insulin resistance with controls (basal, insulin, insulin + palmitate) on the left." (PMID 37494090, 2023). "These cytokines inhibit insulin signaling, resulting in dysfunction and insulin resistance in the adipocyte." (PMID 37297501, 2023). "It mediates decreased insulin sensitivity and results in insulin resistance, fatty liver and lipogenesis." (PMID 37275420, 2023). "Related studies have found that peripheral hyperinsulinemia contributes to increased insulin levels in the brain and further leads to insulin resistance in neurons." (PMID 37867511, 2023). "There is encouraging evidence of the superior effect of berberine alone vs. placebo/no regimen regarding the live birth rate, ovulation rate, androgen levels, decreasing fasting plasma glucose, and insulin levels, as well as the lowering of insulin resistance." (PMID 36676074, 2023). "The effect of insulin is reduced in type 2 diabetes (insulin resistance), so that more insulin must be produced (relative insulin deficiency) to keep blood glucose level constant." (PMID 38074488, 2023). "In the present study, we observed insulin resistance (through elevated fasting insulin levels) and increased liver triglyceride content in response to the HFHC diet treatment." (PMID 37886997, 2023).
Insulin resistance (continued). "AUCinsulin represents the total amount of insulin secretion after oral glucose load and can indicate insulin resistance to some extent." (PMID 38269248, 2023). "This study showed that low SHBG in early pregnancy, which reflects the degree of insulin resistance, was associated with early‐onset GDM and with the need of long‐acting insulin treatment, which is mostly used for fasting hyperglycaemia." (PMID 36484476, 2023). "By enhancing insulin sensitivity and decreasing insulin resistance, acupuncture has the potential to regulate blood sugar levels." (PMID 37600709, 2023). "Gestational diabetes only occurs during pregnancy as a result of an increase in anti-insulin hormones, leading to insulin resistance and elevated blood sugar levels in the mother." (PMID 37513684, 2023). "Fat-specific RICTOR deletion leads to insulin resistance as the mice display elevated levels of circulating insulin but reduced insulin sensitivity at young age." (PMID 36812323, 2023). "Insulin resistance was enabled by the surrogate marker HOMA - IR (Fasting plasma glucose (mmol/l) x plasma fasting insulin(m IU/ml)/22.5)." (PMID 37928491, 2023). "CUR5-8 improved insulin resistance by restoring insulin sensitivity, reducing insulin levels, and lowering homeostasis model assessment-estimated insulin resistance (HOMA-IR) values." (PMID 37762669, 2023). "Acute exposure to bright light (>500–600 lux) in the evening increases insulin resistance and elevates postprandial insulin, glucose, and GLP-1 levels, relative to dim light (<2–5 lux)." (PMID 36768693, 2023). "Insulin signaling inhibits ZFYVE28 expression by inhibiting NOTCH1 via the RAS/ERK pathway, whereas ZFYVE28 expression is elevated due to impaired insulin signaling in insulin resistance." (PMID 37884540, 2023). "In response to insulin resistance, the pancreas initially increases insulin production, resulting in the condition known as hyperinsulinemia." (PMID 37881393, 2023). "We observed that CAND1 KO+/--HFD mice exhibited higher fasting glucose levels, fasting insulin levels, and homeostatic model assessment of insulin resistance (HOMA-IR) compared with WT-HFD mice." (PMID 37528093, 2023). "Excess FFAs play a role in increasing very low-density lipoprotein production and inhibiting insulin clearance, leading to insulin resistance." (PMID 37064684, 2023). "Specifically, vitamin D has been demonstrated to enhance insulin release and decrease insulin resistance in T2D." (PMID 37755259, 2023). "Adipose tissue inflammation impairs insulin signaling and promotes the development of insulin resistance." (PMID 37935669, 2023). "GLUT4 is a major insulin-responsive glucose transporter, which is downregulated in adipose tissues in a state of insulin resistance." (PMID 37033635, 2023). "While most in vivo studies have demonstrated the benefits of AOX supplementation in reducing the severity of glucose intolerance and insulin resistance, it was also shown that excess AOXs negatively affect insulin sensitivity in rodents." (PMID 37237860, 2023). "Further studies including body mass index (BMI), insulin level, insulin resistance and oxidative stress markers for men should also be considered in future studies." (PMID 36983577, 2023). "In terms of mechanism, PI3K/AKT is considered the key regulator in the insulin signaling pathway, and PI3K/AKT pathway inhibition will frequently cause hepatic insulin resistance." (PMID 37569125, 2023). "The authors note that while lean PCOS women exhibit lower instances of insulin resistance and serum insulin levels compared to their obese counterparts, these parameters are still significantly elevated in relation to healthy individuals." (PMID 37881324, 2023). "Insulin resistance refers to a state in which the action of insulin is reduced at physiological insulin concentrations." (PMID 36834911, 2023). "Insulin resistance reduces insulin’s ability to regulate glucose in muscles, adipose cells, and the liver." (PMID 37509481, 2023).